INSR (insulin receptor)
Diseases named in the same sentence as INSR in open-access papers (continued):
Sharing a sentence is not in itself a finding about the gene and the disease.
Hyperinsulinemia (continued). "When ligand/receptors are constantly exposed to insulin, a negative feedback loop down regulates insulin receptor availability to insulin, creating a relative hyperinsulinemia." (PMID 37446104, 2023). "Another strain of mice with impaired insulin receptor function also exhibited insulin resistance and hyperinsulinemia, but without an impact on lifespan." (PMID 37854186, 2023). "The progression of these abnormalities leads to hyperinsulinemia in an effort of pancreatic β-cells to provide the required insulin, which is not reaching cells because of a dysfunction in the insulin receptor signaling pathway." (PMID 36233611, 2022). "The ovarian phenotype we describe in an infant with Donohue syndrome, characterized by minimal residual insulin receptor function, suggests moreover that ovarian effects of extreme hyperinsulinemia are not mediated through the insulin receptor." (PMID 33901270, 2021). "Given that AD patients tend to present hyperinsulinemia and decreased insulin sensitivity, we believe that the beneficial effects of APN in both the OB and the HIPP are mediated by the sensitization of InsR." (PMID 33653273, 2021). "Interestingly, mice exhibiting a β-cell–specific deletion of the insulin receptor (IR) or insulin growth factor 1 receptor (IGF1R) are glucose-intolerant and show fasting hyperinsulinemia." (PMID 32934005, 2020). "Mice lacking the INSR gene suffer from hyperglycemia and hyperinsulinemia, and a large number of studies reveal a decrease in INSR in T2DM patients." (PMID 27763497, 2016). "Whereas muscle-specific insulin receptor knockout does not induce hyperglycemia or hyperinsulinemia, hepatocyte-specific insulin receptor knockout mice exhibit overt hyperglycemia and hyprerinsulinemia." (PMID 26172834, 2015). "Collectively, these results indicate that absence of the insulin receptor in GnRH neurons does not affect peripheral glucose metabolism and that the degree of hyperinsulinemia was similar between genotypes." (PMID 25780937, 2015). "The insulin receptor (INSR) in the human RBC was shown to have the same basic features as in other tissues, a reduced binding of insulin to RBC-INSR was observed in non–insulin-dependent diabetes, and in hypertension with hyperinsulinemia." (PMID 27239515, 2015). "Akt expression was not affected by DEX treatment, even with hyperinsulinemia and upregulated INSR, indicating the unaltered insulin signaling cascade." (PMID 22623960, 2012). "It is well known that impaired insulin receptor (IRS)/AKT signaling leads to defective adipogenesis in obesity and contributes to increased inflammation, which, in turn, hinders glucose disposal, resulting in a compensatory rise in beta-cell insulin production and hyperinsulinemia." (PMID 41532014, 2026). "INSR VUS detected in case 40 may concur with fasting hyperinsulinemia but without functional data, it is not possible to opt for a dominant-negative effect." (PMID 36178555, 2023). "Hyperinsulinemia may desensitize the insulin receptor to suppress glycogenolysis and gluconeogenesis but not DNL." (PMID 37242206, 2023). "Furthermore, we found that the diet‐induced increase in tyrosine phosphorylation on the majority of proteins is independent of hepatic INSR expression and therefore cannot be attributed to hyperinsulinemia alone." (PMID 31464373, 2019). "First, consistent with the ambient postprandial hyperinsulinemia present in MetS mice 1 h after oil gavage, the intestines of these mice, as compared with controls, had much higher levels of phosphorylated AKT, higher mRNA content of the insulin receptor (IR) and insulin receptor substrate 1 (IRS1)." (PMID 26727015, 2016). "It is possible that hyperinsulinemia induces GnRH secretion via activation of the IGF-1 receptor which can bind insulin at high doses, but the reduction in GnRH secretion we observed upon deletion of the IR in the neuron suggests that activation is occurring via insulin receptor signaling." (PMID 25780937, 2015).
Hyperinsulinemia (continued). "However, supplementation with TB protected IUGR piglets from hyperinsulinism and maintained normal metabolism of glycose in the liver of IUGR piglets, and the mRNA expression of INSR and Akt2 was downregulated which corresponded to the decreased concentration of insulin." (PMID 26317832, 2015). "Also, it has been described that hyperinsulinemia in PCOS could possibly be due to defects in the expression and/or activity of proteins downstream from the insulin receptor." (PMID 22390153, 2012). "Chronic hyperinsulinemia, which may result from exaggerated insulin responses to rapidly absorbed starch in high-SAA individuals or from inefficient digestion and prolonged glucose absorption in low-SAA individuals, can downregulate insulin receptor sensitivity and disrupt metabolic homeostasis." (PMID 40806495, 2025). "Hyperactivation of mTOR complex 1 (mTORC1) in response to repeated postprandial hyperinsulinemia may contribute to negative feedback inhibition of insulin receptor substrate (IRS) proteins, particularly IRS-1, impairing downstream insulin signaling via the PI3K-Akt pathway." (PMID 40806495, 2025). "Unlike the liver specific insulin receptor knockout (LIRKO) mouse used in the previous study, our Ffar2-/- mice do not exhibit elevated plasma insulin concentrations suggesting possibly that maternal hyperinsulinemia may be driving the early-age metabolic impacts in the offspring." (PMID 27959892, 2016).
Hyperglycemia (192 papers, 2008 to 2026). An increased concentration of glucose in the blood. "DM includes a group of chronic metabolic derangements featured by hyperglycemia due to absolute or relative insulin deficiency and/or IR that results from insulin receptor or postreceptor defects." (PMID 37163198, 2023). "In particular, muscle hypotonia and hyperglycemia with associated hyperinsulinism led to a clinical suspicion of an insulin receptor (IR)-related severe insulin resistance syndrome." (PMID 29695048, 2018). "In contrast, the hyperglycemia from feeding an ad libitum diet in the presence of insulin deficiency retained liver weight due to an insulin receptor signaling level that was comparable to sham-control rats." (PMID 26060824, 2015). "The induction of ERα mRNA by hyperglycemia was retained in insulin receptor-deficient β-cells, demonstrating independence from direct insulin regulation." (PMID 24498408, 2014). "Key reasons for failure include the high homology between IGF-1R and insulin receptor (IR), where inhibitors may disrupt insulin signaling and cause side effects (e.g., hyperglycemia)." (PMID 41509070, 2025). "Inhibition of the InsR is associated with hyperinsulinemia and hyperglycemia." (PMID 37858153, 2023). "Whole-body knockout of INSR showed reduced cytokine production, proliferation, and migration, as well as increased apoptosis of T cells, although the results from this model were confounded by the underlying hyperglycemia associated with systemic loss of INSR function." (PMID 34981777, 2022). "Mechanistically, TSCF may alleviate hyperlipidemia and hyperglycemia in diabetic mice by regulating the INSR-, GLUT4-, PI3K- and AKT-associated signaling pathways." (PMID 33809821, 2021). "Hyperglycemia is one of the most important risk factors, which can destroy the micrometabolic environment in the retina and reduce the signals from the insulin receptor required for nerve growth, development, and survival, eventually leading to nerve cell apoptosis." (PMID 33117270, 2020). "Importantly, liver-specific insulin receptor-deficient mice (LIRKO mice) exhibit hyperglycemia associated with increased G6pc expression." (PMID 26615883, 2015). "L-asparaginase induces hyperglycemia via depletion of L-asparagine and as a consequence decrement of insulin synthesis; additionally it decreases insulin secretion from pancreatic β-cells, impairs insulin receptor function, and causes hyperglucagonemia." (PMID 24716037, 2014). "Presentation with delayed development and with mild hyperglycemia in our patient can be explained by the heterogeneity of mutations in the insulin receptor.This is the first report of occurrence of a congenital heart disease in a patient of SEIR with RMS phenotype." (PMID 23367497, 2013). "Treatment with the isolated metabolites, particularly Pheophytin a, significantly mitigated hyperglycemia, upregulated insulin receptor and GLUT4 expression, activated the PI3K/AKT signaling pathway, and suppressed TNF-α mediated inflammation." (PMID 41964775, 2026). "Systemic treatment with the insulin-receptor antagonist, S961, can induce β-cell-specific senescence and hyperglycemia in 28-week-old C57BL/6J mice." (PMID 40855115, 2025). "This pathway is characterized by direct inhibitory phosphorylation of insulin receptor substrates, resulting in diminished insulin signaling and exacerbation of hyperglycemia." (PMID 40704318, 2025). "This suggests that chronic hyperglycemia during gestation leads to downregulation of INSR, thus diminishing its signaling capacity and contributing to impaired insulin-mediated vascular responses." (PMID 41373661, 2025). "Linsitinib is a dual inhibitor of IGF-1R and insulin receptor which brings concerns for potential side effects related to the induction of hyperglycemia, which was however only observed in less than 1% of patients." (PMID 39759002, 2024).
Hyperglycemia (continued). "We provide evidence that the hyperglycemia in the old is accompanied by proteolytic cleavage of the extracellular domain of the insulin receptor." (PMID 39418235, 2024). "Hyperglycaemia distorts the insulin/insulin receptor/phosphatidylinositol 3 kinases/GLUT signalling pathway, which results in hyperinsulinaemia and the activation of many inflammatory factors, such as cytokines and adhesion factors." (PMID 39456664, 2024). "Hyperglycemia also downregulates insulin signaling in the brain by attenuating insulin receptor substrates and Akt signaling, leading to impairments in glucose metabolism and plasticity." (PMID 38505757, 2024). "Another study showed insulin receptor knockout in kidney cells caused albuminuria, DKD changes, and hyperglycaemia." (PMID 39698033, 2024). "The inhibition of insulin receptor substrate 2 (IRS2) and insulin receptor (INSR) was predicted to activate hyperglycemia and CVD." (PMID 37569355, 2023). "IGF1R antibodies or inhibitors had been mainly developed for cancer treatment; however, nearly all of them failed owing to their side effects, such as hyperglycemia due to high sequence homology with the insulin receptor." (PMID 37717026, 2023). "A sharp reduction in InsR signaling in the kidney of male animals appears to be more likely to lead to hyperglycemia (due to enhanced gluconeogenesis and a smaller decrease in G6PC and SGLT2)." (PMID 37175762, 2023). "In mice with InsR deleted solely from renal PTs, we found increased mRNA expression for glucose-6-phosphatase (G6P), the terminal enzyme in gluconeogenesis and modest hyperglycemia." (PMID 37175762, 2023). "Studies have shown that hyperglycemia can modulate insulin signaling by impairing insulin receptor activity and Pi3K/AKT signaling." (PMID 36722656, 2023). "Modern studies have shown that berberine can reduce blood glucose in type 2 diabetic patients by increasing insulin receptor expression and increasing glucose efficacy or alleviate hyperglycemia by inhibiting the hepatic glucagon pathway in diabetic mice." (PMID 35399638, 2022). "In the present work, we comprehensively characterized effects of short-term hyperglycemia induced by administration of an insulin receptor antagonist, the S961 peptide, on endothelium and perivascular adipose tissue (PVAT) in mice." (PMID 34207844, 2021). "The reported main side effects of copanlisib are mostly infusion-related including transient hyperglycemia, which is an expected on-target effect of PI3Kα inhibition that is related to insulin-receptor signaling." (PMID 34187401, 2021). "IGF-1 signaling, together with insulin/insulin receptor signaling, mediates cellular proliferation and survival in multiple pathological conditions including hyperglycemia." (PMID 34371877, 2021). "Asparaginase-induced hyperglycemia can be explained by the fact that asparaginase decreases insulin production and insulin-receptor expression." (PMID 34640436, 2021). "In all of our studies, therefore, NPC43 acted as a novel insulin mimetic in the liver to directly activate INSR signaling, thereby inhibiting glucose production and enhancing glucose uptake to mitigate hyperglycemia and glucose intolerance." (PMID 31378829, 2020). "Tyrosine kinase inhibitors (TKIs) such as linsitinib are able to inhibit IGF1R as well as the INSR, leading to toxicities from metabolic complications such as hyperglycemia." (PMID 30653502, 2019). "Acute induction of insulin receptor knockout in adipocytes changed the substrate preference to fat before induction of a diabetic phenotype including hyperinsulinaemia and hyperglycaemia." (PMID 31309261, 2019). "Hyperglycemia disrupts the delicate metabolic environment in the retina and reduced signals from the insulin receptor, which are essential for neuronal development." (PMID 29744359, 2018).
Hyperglycemia (continued). "In the clinical trials of CO-1686 and AZD9291, hyperglycemia has been observed as one of the adverse events, possibly due to the activity against INSR and IGF1R kinases either through themselves or the corresponding metabolites." (PMID 28407693, 2017). "We examined the antidiabetic effect of EPA in insulin receptor mutant (InsrP1195L/+) mice that exhibit high-fat diet (HFD)-dependent hyperglycemia." (PMID 27348201, 2016). "In vivo, S961 administration induces hyperglycemia in wild type animals and closely recapitulates the phenotype of mice with liver-specific insulin receptor deletion." (PMID 27092792, 2016). "Overexpression of miR-15b and/or miR-16 reduced TNFα and SOCS3 levels, while increasing insulin-like growth factor binding protein-3 (IGFBP-3) levels and the phosphorylation of insulin receptor (IR)Tyr1150/1151 in REC cultured in hyperglycemia." (PMID 25888955, 2015). "Characterization of overt hyperglycemia in insulin receptor mutant (InsrP1195L/+) mice exposed to HFD (InsrP1195L/+/HFD mice) revealed increased glucose-6-phosphatase (G6pc) expression in liver and increased gluconeogenesis from glycerol." (PMID 26615883, 2015). "Prenatal hyperglycemia induces strong changes in later hypothalamic expression of INSR, LEPR, GLUT1, and GLUT3 mRNA." (PMID 25811618, 2015). "Knocking out insulin receptor in the proximal tubule epithelial cells results in hyperglycemia due to an increase in gluconeogenesis." (PMID 26465605, 2015). "Remarkably, targeted deletion of the renal proximal-tubule insulin-receptor in mice promotes hyperglycemia, up regulation of glucose 6 phosphatase and gluconeogenesis." (PMID 24839967, 2014). "Hyperglycemia can lead to increased platelet reactivity and not only hyperglycemia but insulin can also directly control platelet function by a functional insulin receptor found on human platelets." (PMID 24883111, 2014). "Of note, a recent paper reported a targeted deletion of the renal proximal-tubule insulin-receptor in mice promoted hyperglycemia, up regulation of glucose 6 phosphatase and gluconeogenesis." (PMID 24839967, 2014). "ESP or OST-PTP phosphatase dephosphorylates and inactivates the osteoblast insulin receptor and inhibits the metabolic function of osteocalcin, resulting in reduced insulin secretion, hyperglycemia and reduced glucose tolerance." (PMID 24839967, 2014). "The liver-specific glucokinase knockout mouse experiences long-term hyperglycemia, which induces decreased levels of insulin receptor." (PMID 24447392, 2014). "We have previously reported that hyperglycemia significantly reduced insulin receptor phosphorylation on tyrosine 1150/1151, which was restored following treatment with a β-adrenergic receptor agonist, Compound 49b." (PMID 23894672, 2013). "O-GlcNAcylation stimulates activation of the p38, ERK, and JNK pathways in response to hyperglycemia and contributes to the reduced activation of the insulin receptor and IR substrate, phosphoinositol-3-kinase, and Akt." (PMID 22489274, 2012). "The ST3GAL2 deficiency disrupted insulin signaling by impairing insulin receptor-mediated phosphorylation in adipose tissue but not liver or skeletal muscle, leading to hyperglycemia and insulin resistance." (PMID 41301440, 2025). "However, hyperglycemia has been shown to suppress the expression of mitochondrial acetyl-CoA synthetase 3, leading to mitochondrial dysfunction and insulin receptor impairment in hypothalamic neurons." (PMID 40979948, 2025). "Moreover, studies with the liver‐specific insulin receptor KO (LIRKO) model revealed FGF21 treatment to normalise hyperglycaemia in mice by increasing energy metabolism in brown fat." (PMID 39962359, 2025). "Treatment of old rats for 14 days with a pancreatic trypsin inhibitor (tranexamic acid) attenuates the breakdown of the mucin barrier, reduces the accumulation of digestive enzymes in peripheral organs, collagen degradation, and reduces insulin receptor cleavage and hyperglycemia in old rats." (PMID 39418235, 2024).